TBX3 (T-box transcription factor 3)
Diseases named in the same sentence as TBX3 in open-access papers (continued):
Sharing a sentence is not in itself a finding about the gene and the disease.
breast carcinoma (continued). "TBX3 is a T-box transcription factor repressor that is elevated in metastatic breast cancer and is believed to promote malignancy of tumor cells, possibly by promoting cell survival and epithelial-mesenchymal transition." (PMID 27553211, 2016). "The T-box transcription factor 3 (13,910 bp) is expressed in mammary tissues and plays therefore a context-dependent role in mammary gland development as well as in mammary tumor genesis." (PMID 26920143, 2016). "An increased level of TBX3 was observed in blood plasma from patients with higher stage breast cancer." (PMID 26579496, 2015). "A critical role of TBX3 for cell migration was also demonstrated in the MCF7 breast cancer cell line." (PMID 26579496, 2015). "When the entire ICGC data set was analyzed for TBX3 ORF mutations (ratio of complete ICGC to BRCA-US dataset ~12/1), 21 frameshift mutations were found, 15 of which arose in breast cancer (8.5-fold enrichment)." (PMID 26579496, 2015). "Our analysis of TBX mutations in the ICGC data set showed that in breast cancer (BRCA-US), TBX3 was the most frequently mutated TBX gene among the 16 human paralogs." (PMID 26579496, 2015). "The preponderance of these particular types of mutations in TBX3 versus the other TBX genes points to an important role of TBX3 in breast cancer progression." (PMID 26579496, 2015). "Using the MuSIC tool they identified TBX3 as “significantly mutated gene” (SMG) with an increased mutation rate relative to background, in particular in breast cancer." (PMID 26579496, 2015). "In human breast cancer cell lines and primary tissue, TBX3 mediates the effect of estrogen to induce the formation and expansion of cancer stem-like cells." (PMID 26579496, 2015). "The closely related T-box transcription factors TBX2 and TBX3 are frequently overexpressed in melanoma and various types of human cancers, in particular, breast cancer." (PMID 26579496, 2015). "XRCC6 interacts with Msx2 (a known TBX3 interactor) and Runx2 (a TBX3 target) and mutations in XRCC6 are associated with breast cancer risk and estrogen exposure." (PMID 24675841, 2014). "For instance, in ER+ breast cancer cell lines, Tbx3 expression was dependent on both estrogen and FGF signaling." (PMID 25343378, 2014). "Tbx3 is a transcriptional repressor with an important role in embryonic development of the mammary gland and a high expression in certain breast cancers, but its role in the different cell types of adult mammary epithelium has yet to be explored." (PMID 25343378, 2014). "In breast cancer, high nuclear and cytoplasmic expression of Tbx3 was found in a subset of cells in primary tumors and high transcriptional Tbx3 levels in human breast tumors correlated strongly with ER expression." (PMID 25343378, 2014). "Out of the top ten mutated genes in the large breast cancer investigation of The Cancer Genome Atlas (TCGA), we found mutations in seven of these (PIK3CA, GATA3, MAP3K1, MLL3, CDH1, PTEN, TBX3)." (PMID 24998755, 2014). "TBX3 expression is necessary for breast organogenesis and its aberrant expression has been identified in breast cancers, yet little is known about its function in epithelial cells of the adult human breast." (PMID 25350852, 2014). "Given the current uncertainty about an anti- or pro-tumorigenic role of Tbx3 in breast cancer, it will be interesting to determine the relevant targets for Tbx3 specifically in hormone-sensing cells." (PMID 25343378, 2014). "Despite the vast distance, a previous study has suggested rs1292011 to be potentially mediating ER-positive breast cancer through an effect on TBX3 due to significant elevation of expression in plasma from individuals with breast cancer." (PMID 24920305, 2014). "In breast cancer, FGF signalling regulates Tbx3 and Tbx3 cooperates with c-Myc and Ras associated transformation." (PMID 23082988, 2012).
breast carcinoma (continued). "Identifying the mechanism by which TBX3 promotes accelerated mammary gland development will help to further elucidate its possible role in breast cancer development." (PMID 22039763, 2011). "Our results showed that 430 gene promoters are bound by TBX3 in the MCF7 breast cancer cell line (unpublished data)." (PMID 22039763, 2011). "The TBX3 gene is located at the 12q24 region which is frequently amplified in a variety of malignancies including breast cancer." (PMID 22039763, 2011). "More recently, it has been shown that PMA-induced up-regulation of TBX3 contributes to breast cancer cell migration." (PMID 22039763, 2011). "TBX3 is over-expressed in various breast cancer cell lines as well as cancer tissue and has been found to contribute to breast cancer cell migration." (PMID 22039763, 2011). "TBX3 is mislocalized to the cytoplasm in primary breast cancer tissues and serum TBX3 protein levels were also found to be abnormally high in early stage breast cancer patients." (PMID 22039763, 2011). "Studies have suggested a role for Tbx3/TBX3 in regulating the self-renewal of mouse embryonic stem (ES) cells as well as breast cancer stem-like cells." (PMID 22039763, 2011). "Additionally, the reported role in breast cancer of fetal mammary developmental genes, such as TBX3, WNT-10b, FGF10, and LEF1, highlights their potential clinical relevance as biomarkers and therapeutic targets." (PMID 40001874, 2025). "Indeed, studies have reported dysregulation of crucial fetal mammary developmental genes [e.g., T-box transcription factors (TBX2 and TBX3)] in human breast cancer cells in vitro." (PMID 40001874, 2025). "Interestingly, TBX3 has been shown to maintain mouse embryonic stem cell pluripotency in the same manner that it stimulates breast cancer stem cells." (PMID 40001874, 2025). "Interestingly, activation of both the WNT/β-catenin and FGF signaling pathways have been shown to directly upregulates the expression of TBX3, thereby leading to breast cancer stem cell expansion." (PMID 40001874, 2025). "In addition, TBX2 and TBX3 have been reported to be overexpressed in certain cancer types, including endometrial, cervical, ovarian, breast carcinoma." (PMID 38413457, 2024). "Elevated TBX3 mRNA levels strongly correlated with (ER)-positive breast cancer tumors." (PMID 39358558, 2024). "Indeed, if on the one hand the concomitant high SIRT6 and low TBX3 expression predicts better prognosis in basal-like breast cancer, on the other, it is indicative of poor prognosis in HER2-positive breast cancer patients." (PMID 38081972, 2023). "Altogether, these data suggest that TBX3 suppression or loss mimics SIRT6-OE and amplification in HER2-positive breast cancer and demands for further future specific investigations about their interaction/co-regulation and their role in therapy resistance, relapse and lung metastasis." (PMID 38081972, 2023). "Mechanistically, TOPK was found to mediate hypoxia‐induced epithelial‐mesenchymal transition (EMT) and the invasion of NSCLC cells via the HIF‐1a/snail axis, and promote the EMT and invasion of breast cancer cells by upregulating TBX3 in TGF‐β1/Smad signalling." (PMID 37226642, 2023). "TBX3 mutations were not among the recurrent mutations in a large Nigerian breast cancer cohort with 129 patients, in agreement with our finding that they are more common in EA patients." (PMID 37902422, 2023). "Interestingly, estrogen signaling expands breast CSCs in MCF7 breast cancer cells through a paracrine FGF/FGFR/TBX3 signaling pathway, suggesting a role for Tbx3 in promoting stemness." (PMID 35846378, 2022).
breast carcinoma (continued). "TBX3, a mostly cytoplasmic protein in both normal and breast cancer tissues, is significantly overexpressed in the latter, and thus, could serve as a potential diagnostic marker of breast cancer cells." (PMID 36358654, 2022). "Furthermore, our data indicate that TBX3 performs these repressive impacts by recruitment of histone deacetylases, as demonstrated in breast cancer cells." (PMID 34807923, 2021). "Collectively, the described changes involving TBX3iso1-dependent promotion of angiogenesis may thus serve as an adaptive mechanism within breast cancer cells, potentially explaining differences in tumor formation rates between TBX3 isoforms in vivo." (PMID 31570773, 2020). "Indeed, in MCF7 breast cancer cells, we showed that TBX3 repression promoted colony formation and in vivo tumor formation." (PMID 31910858, 2020). "Both MYC and TBX3 play important roles in breast cancer and BCSCs." (PMID 33217982, 2020). "TBX3 has been shown to promote tumor metastasis and the migration of breast cancer cells." (PMID 30979887, 2019). "We have previously established a role for TBX3 in the invasiveness of breast cancer." (PMID 30697731, 2019). "Large‐scale genomics consortia have previously identified a number of breast cancer driver genes, including TBX327; indeed, TBX3 mutations account for ulnar–mammary syndrome 28, and, in breast cancer, appear to result in the loss of transcriptional repressor function." (PMID 29344954, 2018). "Overexpression of mature luminal regulator TBX3 in breast cancer cell lines has been observed previously, especially in cells with estrogen-receptor positive status, e.g., MCF7, and it has been shown that estrogen induces TBX3 expression, increasing number of stem-like cells." (PMID 30344242, 2018). "Overall, these results indicate that TBX3 (isoform 1 or 2) expression can promote progression in a model of early breast cancer by altering cell properties involved in cell survival/colony formation and invasiveness, as well as key regulatory and EMT/invasiveness-related gene expressions." (PMID 27553211, 2016). "Furthermore Douglas and Papaioannou observed TBX3 overexpression in estrogen-receptor-positive breast cancer cell lines." (PMID 26920143, 2016). "The relative expression of TBX3 was assessed in the 21T cell lines which were derived from an individual patient and represent three distinct stages of breast cancer progression: 21PT, atypical ductal hyperplasia; 21NT, ductal carcinoma in situ; and 21MT-1, invasive mammary carcinoma." (PMID 27553211, 2016). "Here we examined whether either or both isoforms of TBX3 could influence breast cancer progression, in particular the transition from non-invasive to invasive disease." (PMID 27553211, 2016). "This concentration of frameshift TBX3 ORF mutations in breast cancer is highly non-random (p < 10−7)." (PMID 26579496, 2015). "TBX3 was reported to be overexpressed in breast cancer cell lines and in primary cancer tissue." (PMID 26579496, 2015). "Indeed, estrogen has recently been reported to expand breast cancer stem-like cell cells through upregulation of TBX3." (PMID 25350852, 2014). "Another T-box factor, TBX3, can cause absent or hypoplastic mammary glands and it is under investigation in breast cancer carcinogenesis." (PMID 23984174, 2013). "In addition to its role in mammary gland development, various studies have also supported a role for Tbx3 in breast cancer development." (PMID 22039763, 2011).
breast carcinoma (continued). "Besides Tbx3's role in early mammary gland development, various studies have also supported a role for Tbx3 in breast cancer development." (PMID 22039763, 2011). "On the other hand, Tbx3 is over-expressed in a variety of cancers, including breast cancer." (PMID 22039763, 2011). "Taken together, these studies suggest that a dysregulation of TBX3 expression may contribute to breast cancer development." (PMID 22039763, 2011). "Due to its role in promoting proliferation of mouse ES cells and breast cancer stem-like cells as well as its requirement for early mammary gland development, TBX3 may also play a role in regulating mammary stem cell proliferation." (PMID 22039763, 2011). "Identifying whether TBX3 directly promotes breast cancer development and the mechanism by which it does this is important for understanding mammary development as well as the perturbations that may lead to breast cancer." (PMID 22039763, 2011). "Expression of Tbx3 has been shown to promote the proliferation of breast cancer stem cells in vitro, suggesting that Tbx3 may also promote mammary stem cell proliferation." (PMID 22039763, 2011). "Moreover, TBX3 is over-expressed in various breast cancer cell lines as well as primary breast cancer tissues." (PMID 22039763, 2011). "A dataset containing primary breast cancer expression data was assembled from the literature and used to search genes functionally related to a gene of known function, PK, and for the prediction of TBX3 functional partners." (PMID 19828084, 2009). "TBX3 is overexpressed in some breast cancer cell lines, and high levels of expression of a truncated form of TBX3 are found in the plasma of early stage breast cancer patients." (PMID 16933995, 2006). "The physiological subcellular localization of TBX21 is regulated by PD1 in T-cells and aberrant enhancement of nuclear import from the cytoplasm has been reported for TBX2 in breast cancer cells, indicating that this type of regulation may play a role for the related TBX3 as well." (PMID 34807923, 2021). "Our examination of TBX3 by immunohistochemistry in two independent patient cohorts revealed that levels are highest in hormone receptor‐positive, low‐grade DCIS (and co‐existing CCLs) and are associated with the extent of invasion in early‐stage breast cancers." (PMID 30697731, 2019). "In addition, The TBX3 is overexpressed in a number of breast cancer cell lines and could serve as a biomarker." (PMID 26920143, 2016). "The position of breast cancer frameshift mutations in TBX3 was highly non-random." (PMID 26579496, 2015). "Also, over-expression of TBX3 is associated with an increased number of mammary stem-like cells suggesting another mechanism by which TBX3 may promote mammary gland hyperplasia and contribute to breast cancer development." (PMID 22039763, 2011). "Although many studies have shown that a dysregulation of TBX3 expression may contribute to cancer progression, no direct evidence shows TBX3 causes breast cancer." (PMID 22039763, 2011). "Although many studies have shown that a dysregulation of TBX3 expression may contribute to cancer progression, no direct evidence shows that TBX3 causes breast cancer." (PMID 22039763, 2011). "Overall, our data suggests that over-expression of TBX3 may contribute to breast cancer development by promoting accelerated mammary gland development through the inhibition of the NF-κB pathway and stimulation of both mammary epithelial cell and stem-like cell proliferation." (PMID 22039763, 2011). "Previous study reported that ZFHX3 is involved with proliferation of breast cancer cells by enhancing MYC and TBX3 transcription, which was well recapitulated in our data." (PMID 40312397, 2025). "For example, in breast cancer and melanoma, TBX2 functions as a powerful pro‐proliferative factor while TBX3 promotes invasion and migration by repressing TBX2." (PMID 40717225, 2025).
breast carcinoma (continued). "Additionally, BMP4 overexpression has been shown to inversely correlate with TBX3 expression in mammary tissues; however, it remains unclear whether this relationship holds true in breast cancer, particularly given that both BMP4 and TBX3 exhibit pro-proliferative properties in breast cancer." (PMID 40001874, 2025). "For instance, SIRT6 represses the expressions of the T-box transcription factor 3 (Tbx3) by deacetylation of H3K9ac, which is predictive of poor prognosis in HER2-positive breast cancer patients." (PMID 39709438, 2024). "Here, we identified TBX3 as a target downregulated by SIRT6 in both Delta16HER2- and HER2-positive breast cancer models, and we found that concomitant high SIRT6 and low TBX3 expression predicts poor prognosis in HER2-positive breast cancer patients." (PMID 38081972, 2023). "Accordingly, the silencing of TBX3 promotes migration and self-renewal of both human Delta16HER2- and HER2-positive breast cancer cells in vitro." (PMID 38081972, 2023). "In this regard, even if the expression of TBX3 and SIRT6 is inversely correlated in both basal-like and HER2-positive breast cancer patients, their paired expression levels have opposite predictive meanings in these two cancer subtypes." (PMID 38081972, 2023). "HOTAIR uses miR-The 206/TBX3 axis maintains the stemness of ovarian cancer stem cells and HOTAIR regulates the proliferation of breast cancer cells through the miR-206-mediated BCL-W signaling pathway." (PMID 36115953, 2022). "TBX3 modulates early embryo and mammary gland development and breast cancer initiation and progression via multiple mechanisms such as the paracrine FGF/FGFR/TBX3 signaling pathway." (PMID 33217982, 2020). "Such a pro-proliferative function involves an enhanced breast cancer stemness and transcriptional upregulation of two factors that have a well-established role in breast cancer, MYC and TBX3." (PMID 33217982, 2020). "TBX3 and SNAI2 mRNA levels were significantly lower in high‐grade breast cancers than in low‐ and intermediate‐grade breast cancers (p < 0.001), consistent with our immunohistochemical data." (PMID 30697731, 2019). "Estrogen regulates breast cancer stem cells through fibroblast growth factor, its receptor and T-box transcription factor (FGF/FGFR/TBX3)." (PMID 31114446, 2019). "In addition, another study identified Tbx3 as a novel target of tumor suppressor miR-206 and characterized the miR-206/Tbx3 signaling pathway, which is involved in the proliferation, invasion and maintenance of the cancer stem cell population in breast cancer cells." (PMID 28036274, 2017). "Using microarray analysis, we previously identified T-box transcription factor 3 (TBX3) as a potential regulator of progression from DCIS to IMC, using the 21T cell lines which represent distinct stages of breast cancer progression." (PMID 27553211, 2016). "Our data suggest that, in breast cancer cells, YAP1/β-catenin complex with TBX3, which phenocopies TBX5 at BCL2L1 and BIRC5 but additionally promotes cMYC expression, potentially by combining known TEAD- and TBX3-binding elements." (PMID 26549256, 2015). "In the breast cancer cell line MCF-7 and in vertical growth phase melanoma cell lines, both of which express TBX3 endogenously, it is knock-down of TBX3 that promotes proliferation." (PMID 26579496, 2015). "Numerous overexpression studies have suggested a role for TBX3 in breast cancer (and references therein) and recent papers have reported the tumorigenic and proinvasive effects of overexpressed TBX3 in melanoma cells which may derive in part from TBX3 repression of E-cadherin expression." (PMID 24876127, 2014).